BCL11A (BCL11 transcription factor A)
Description:
Transcription factor. Associated with the BAF SWI/SNF chromatin remodeling complex. Binds to the 5'-TGACCA-3' sequence motif in regulatory regions of target genes, including a distal promoter of the HBG1 hemoglobin subunit gamma-1 gene. Involved in regulation of the developmental switch from gamma- to beta-globin, probably via direct repression of HBG1; hence indirectly repressing fetal hemoglobin (HbF) level. Involved in brain development. May play a role in hematopoiesis (By similarity). Essential factor in lymphopoiesis required for B-cell formation in fetal liver (By similarity). May function as a modulator of the transcriptional repression activity of NR2F2 (By similarity).
Synonyms: CTIP1; EVI9; ZNF856; BCL11A-XL; BCL11A-L; BCL11A-S; HBFQTL5; SMARCM1; DILOS
Tractability: PROTAC: UniProt records ubiquitination sites on it; ubiquitination databases record sites on it; its protein half-life has been measured.
Gene: Protein-coding gene on chromosome 2 (60,450,520 to 60,554,467, reverse strand). Ensembl gene ENSG00000119866.
Subcellular location: Cytoplasm; Nucleus; Chromosome; Nucleus matrix (Isoform 1); Cytoplasm (Isoform 2); Cytoplasm (Isoform 3)
Subcellular location (Human Protein Atlas): Nucleoplasm; Nuclear bodies
Pathways (Reactome):
Chromatin organization: Formation of neuronal progenitor and neuronal BAF (npBAF and nBAF); Formation of the embryonic stem cell BAF (esBAF) complex
Disease: ALK mutants bind TKIs; Signaling by ALK fusions and activated point mutants
Gene Ontology:
Molecular function: DNA-binding transcription repressor activity, RNA polymerase II-specific; RNA polymerase II cis-regulatory region sequence-specific DNA binding; DNA-binding transcription factor activity; protein kinase binding
Biological process: negative regulation of transcription by RNA polymerase II; negative regulation of dendrite development; protein sumoylation; regulation of transcription by RNA polymerase II; cellular response to L-glutamate; negative regulation of branching morphogenesis of a nerve; negative regulation of dendrite extension; negative regulation of neuron remodeling; positive regulation of gene expression
Cellular component: chromosome; nuclear body; nuclear matrix; nucleoplasm; SWI/SNF complex; cytosol; nucleus; cytoplasm; postsynapse
Genetic constraint (gnomAD): Loss-of-function variants: 2 observed, 50.38 expected, observed/expected ratio (o/e) 0.0397, 90% interval 0.015 to 0.12. The upper end of that interval is the gene's LOEUF score, 0.12, which puts it in group 1 of 6, group 1 being the genes least tolerant of losing a copy. Missense variants: 805 observed, 1,139.3 expected, observed/expected ratio (o/e) 0.71, 90% interval 0.67 to 0.75. Synonymous variants: 459 observed, 473.89 expected, observed/expected ratio (o/e) 0.97, 90% interval 0.9 to 1.05.
Gene-disease validity (ClinGen):
ClinGen rates the evidence that BCL11A causes each of these diseases.
Dias-Logan syndrome (autosomal dominant): Definitive. Any BAFopathy in which the cause of the disease is a mutation in the BCL11A gene.
Cancer hallmarks: cell replicative immortality (promotes)
Homologues: Orthologues: chimpanzee BCL11A (100% identical), pig BCL11A (99% identical), mouse Bcl11a (99% identical), rat Bcl11a (99% identical), rabbit BCL11A (98% identical), macaque BCL11A (98% identical), guinea pig BCL11A (98% identical), dog BCL11A (91% identical), tropical clawed frog bcl11a (86% identical), zebrafish bcl11aa (78% identical). Paralogues in human: BCL11B (63% identical), SALL3 (17% identical), HIVEP1 (17% identical), SALL1 (17% identical), HIVEP3 (17% identical), HIVEP2 (16% identical), SALL4 (15% identical), ZNF536 (15% identical), RREB1 (13% identical), SALL2 (12% identical), ZNF217 (11% identical), ZNF516 (11% identical), and 2 more.
Diseases named in the same sentence as BCL11A in open-access papers:
BCL11A is named in the same sentence as 150 diseases in open-access papers, as found by Europe PMC text mining. Sharing a sentence is not in itself a finding about the gene and the disease. The quoted sentences say what the papers report.
sickle cell disease (49 papers, 2013 to 2026). Sickle cell anemias are chronic hemolytic diseases that may induce three types of acute accidents: severe anemia, severe bacterial infections, and ischemic vasoocclusive accidents (VOA) caused by sickle-shaped red blood cells obstructing small blood vessels and capillaries. "Our analysis of missense variants causing loss-of-function in vivo illuminates mechanisms by which BCL11A silences HbF and also suggests potential therapeutic avenues for HbF induction to treat sickle cell disease and β-thalassemia." (PMID 34634037, 2021). "Genome-wide association studies (GWAS) have linked BCL11A to fetal globin level, which directly associates with the clinical severity of sickle cell disease and β-thalassemia." (PMID 33187090, 2020). "In sickle cell disease patients, the HbF level elevation is associated with three quantitative trait loci (QTLs), BCL11A, HBG2 promoter, and HBS1L-MYB intergenic region." (PMID 28280727, 2017). "Two studies, one in a normal population and the other in sickle cell anemia, showed that BCL11A, the HBS1l-MYB interval and variants in HBB were associated with HbA2 level." (PMID 26215470, 2015). "Inactivating mutations in the BCL11A gene are associated with sickle cell disease and β-thalassemias, and it was subsequently shown that BCL11A is a master regulator of fetal haemoglobin switching." (PMID 23975195, 2013). "This study focused on two therapeutically relevant genes, PCSK9 and BCL11A, which are targets for cholesterol reduction and treatment of β-thalassemia and sickle cell disease, respectively." (PMID 39275984, 2024). "Studies showed that knocking out BCL11A in mouse models not only corrected sickle cell disease phenotypes but also mitigated disease symptoms." (PMID 36992422, 2023). "Esrick, Williams and colleagues used their LV-producing shRNAmir to the mRNA of BCL11A LV in a clinical trial for sickle cell disease." (PMID 36992422, 2023). "It provided therapeutic benefits in alleviating sickle cell disease symptoms and demonstrated success for erythroid-specific BCL11A knockdown in preventing toxic effects in HSCs during engraftment." (PMID 36992422, 2023). "With the same principle post-transcriptional genetic silencing of BCL11A was applied in six patients with sickle cell disease leading to broad distribution of HbF with significant reduction or absence of clinical manifestations." (PMID 37545694, 2023). "MicroRNA-adapted short hairpin RNAs (shRNAmir) have been incorporated into LVs to promote the silencing of the regulatory gene BCL11A for therapeutic benefits in sickle cell disease." (PMID 36992422, 2023). "At BCL11A we used PE2 to disrupt the GATA1 binding motif within the BCL11A erythroid enhancer that results in the induction of fetal γ-globin in erythroid progenitors and can ameliorate β-globinopathies like sickle cell disease and β-thalassemia." (PMID 37246708, 2023). "Like the use of short hairpin RNA (shRNA) delivered by LV to silence the BCL11A mRNA in sickle cell disease, this feature can be implemented in the current IDLV setup with delayed or controlled transcription level to limit the transgenes expression." (PMID 35979475, 2022). "Clinical trials are currently seeking to target BCL11A for induction of fetal hemoglobin to treat individuals impacted by sickle cell disease and β-thalassemia." (PMID 34634037, 2021). "Variation in the BCL11A gene ameliorates the severity of sickle cell disease (SCD) and β-thalassemia (β-thal)." (PMID 30768627, 2019). "B-cell lymphoma/leukaemia 11A (BCL11A) is a transcriptional repressor of foetal haemoglobin (HbF) and an ameliorating factor in sickle cell disease (SCD) and β-thalassemia (β-thal)." (PMID 30768627, 2019). "Disruption of bcl11a in sickle mice abrogates the phenotype of sickle cell disease; about 30 % HbF is present in each sickle erythrocyte." (PMID 26215470, 2015).
sickle cell disease (continued). "Based on these data, together with data from animal models, repressors of BCL11A are under development for the treatment of sickle cell disease." (PMID 23696745, 2013). "Research has established that dysfunctions in TR2/TR4 are implicated in β-thalassemia and sickle cell disease (SCD): β-thalassemia is associated with the defective silencing of γ-globin genes, while in SCD, TR2/TR4 antagonizes BCL11A to reactivate fetal hemoglobin (HbF) expression." (PMID 40563438, 2025). "Indeed, as selective knockdown of BCL11A has become a novel therapeutic strategy to treat sickle cell disease, a further understanding of this gene will become more important beyond rare cases of children with DLS/BCL11A-ID." (PMID 40772033, 2025). "Hence, the ZNF410 and BCL11A shRNAmiR vector shows a greater potential and application in both sickle cell disease and β-thalassemia therapy." (PMID 36992422, 2023). "HRI has been proven to increase fetal hemoglobin production via diminishing the expression of BCL11A, and this may be a potential therapeutic target for sickle cell disease." (PMID 37509133, 2023). "Importantly, knock down of BCL11A in transgenic sickle cell disease mice stimulated therapeutic levels of fetal globin, suggesting the importance of BCL11A in hemoglobinopathy treatments." (PMID 33187090, 2020). "Alternatively, erythroid-specific knockdown of BCL11A using shRNA to reactivating HbF production of sickle cells disease could be a therapeutic option that would be beneficial in β-thalassaemia patients." (PMID 31113996, 2019). "BCL11A is a transcriptional regulator that suppresses the expression of γ-globin, and thus the knockout of BCL11A has been proposed as an approach to treat both sickle cell disease and β-thalassemia." (PMID 26755333, 2016). "Another example is BCL11A and persistence of fetal hemoglobin in sickle cell anemia." (PMID 23696745, 2013). "Also, CRISPR/Cas9 was utilized to modify the BCL11A enhancer sequence in hematopoietic stem cells (HSCs), leading to reduced BCL11A enhancer expression and increased production of fetal hemoglobin and gamma-globin, benefiting sickle cell disease and transfusion-dependent beta-thalassemia patients." (PMID 38186450, 2023). "An erythroid-specific enhancer of BCL11A located in an intron of the BCL11A gene is currently the target of multiple gene therapy trials aimed at restoring high levels of fetal hemoglobin to ameliorate disease in beta-hemoglobinopathies (see ‘fetal hemoglobin’ and ‘sickle cell disease’)." (PMID 36826849, 2023). "Genome-wide association studies (GWAS) have found that genetic variants at the BCL11A locus are associated with fetal hemoglobin expression levels, and targeting BCL11A could prevent or ameliorate complications of sickle cell disease by regulating γ-globin expression levels." (PMID 35388006, 2022). "In some studies, the CRISPR-Cas9 technique has been utilized to target BCL11A enhancers in CD34+ cells, which were subsequently reintroduced into patients with β-thalassemia and sickle cell disease, leading to successful treatment 52,53." (PMID 40083704, 2025). "Overall, efforts from the last decades have shed enough light on the mechanisms that orchestrate hemoglobin switching for developing gene therapy approaches targeting such discovered regulators (e.g., BCL11A, ZNF410) for sickle cell disease and β-thalassemia." (PMID 36992422, 2023). "The BCL11A shRNAmir LV, carrying a short 1.4 kb LCR with HS2 and HS3 elements, was studied in vivo using the Berkeley-sickle cell disease mouse model for gene therapy." (PMID 36992422, 2023). "The B-cell CLL/lymphoma 11A (BCL11A) is a zinc-finger transcription factor known to regulate gamma-globin and HbF levels in human erythroid cells as well as to rescue the sickle cell disease phenotype in a murine model through the activation of HbF." (PMID 28768505, 2017). "Comparable marker contributions to baseline HbF were reported for BCL11A and HBB in adult sickle cell disease." (PMID 23409025, 2013).
sickle cell disease (continued). "Sickle cell disease patient HSPCs that have been treated with a vector containing both a ZNF410 and a BCL11A shRNAmiRs and differentiated into erythrocytes led to an increase of 10% HbF and a significant decrease of sickled cells in comparison to BCL11A shRNAmiR only vector treated cells." (PMID 36992422, 2023).
breast cancer (29 papers, 2013 to 2025). A primary or metastatic malignant neoplasm involving the breast. "It indicates that the doxorubicin induces the dysregulation of hiPSC-CMs derived RAD9A, HSPA1B, GATA2, IGF2R, CD200, ERCC8, and BCL11A genes that are associated with the pathogenesis of doxorubicin-induced cardiotoxicity in breast cancer patients." (PMID 37684436, 2023). "It has been shown that BCL11A is linked to breast cancer cell carcinogenesis, proliferation, invasion, and metastasis by activating Wnt/-catenin signalling." (PMID 34976314, 2022). "Bcl11a is a well-known proto-oncogene with BCL11A overexpression found to be associated with enhanced invasion and metastasis across multiple cancer types such as breast cancers, hematological malignancies, glioblastoma, or laryngeal squamous cell carcinoma." (PMID 35805190, 2022). "Two somatic mutations in BCL11A have been reported in breast cancer." (PMID 23506684, 2013). "According to research, BCL11A expression levels decreased with increasing histological malignancy in breast cancer cases as well as cell lines." (PMID 40051609, 2025). "In TNBC, B-cell CLL/lymphoma-11A (BCL11A) is a transcription factor that contributes to maintaining the chemo-resistant breast cancer stem cell population through its interaction with RBBP4." (PMID 41278204, 2025). "In contrast, long non-coding RNA uc.57 decreased BCL11A levels in the breast cancer cells surrounding the tumor." (PMID 37185699, 2023). "This allowed researchers to elucidate the specific role of BCL11A in maintaining the activity of breast cancer stem cells." (PMID 38028543, 2023). "Recently, the pathogenetic role of BCL11A was also highlighted in solid tumors (e.g., lung, prostate, breast cancer, endometrial carcinoma, laryngeal squamous carcinoma)." (PMID 36030436, 2023). "Elevated expression levels of BCL11A have been reported in many cancers, including breast cancer, prostate cancer, colorectal cancer and B-cell lymphomas and leukemias." (PMID 37372998, 2023). "In the mouse mammary gland, BCL11A is part of a specific subsets of embryonic mammary genes, silenced in adult epithelia and reactivated in mouse and human basal-like breast cancer." (PMID 36030436, 2023). "The aim of this study was to investigate the expression pattern of BCL11A in breast cancer (BC) cases and mastopathy samples and to correlate the results with the clinicopathological data." (PMID 37185699, 2023). "The aberrant expression of BCL11A has been reported in acute myeloid leukemia, natural killer/T-cell lymphoma, breast cancer, lung cancer, and so on." (PMID 35909289, 2022). "A recent study demonstrated that BCL11A enhanced tumor formation and cancer cell mobility by activating the Wnt/β-catenin signaling pathway in breast cancer stem cells." (PMID 33403048, 2021). "For example, a BCL11A peptide inhibitor that blocks the recruitment of RBBP4-BCL11A complexes to BCL11A-targeted genes decreases aldehyde dehydrogenase-positive breast cancer stem cells (BCSCs)." (PMID 34736517, 2021). "High expressed SNHG16 can suppress hsa-miR-190b, which leads to increased expression of BCL11A, an oncogene in breast cancer." (PMID 33344235, 2020). "Recently, BCL11A was identified highly expressed in TNBC through the analysis of the METABRIC (Molecular Taxonomy of Breast Cancer International Consortium) and TCGA (The Cancer Genome Atlas) databases, which was verified by qRT–PCR and immunohistochemistry." (PMID 31654056, 2019). "As a novel breast cancer gene, high expression of BCL11A significantly correlates with TNBC subtypes and high histological grade." (PMID 31654056, 2019). "It thus appears shikonin reduces tamoxifen resistance of MCF-7R breast cancer cells by inducing uc.57, which downregulates BCL11A to inhibit PI3K/AKT and MAPK signaling pathways." (PMID 29179465, 2017).